GEMIN4 (gem nuclear organelle associated protein 4)
Diseases named in the same sentence as GEMIN4 in open-access papers:
GEMIN4 is named in the same sentence as 26 diseases in open-access papers, as found by Europe PMC text mining. Sharing a sentence is not in itself a finding about the gene and the disease. The quoted sentences say what the papers report.
lung carcinoma (5 papers, 2016 to 2023). "Several prior studies found the association between GEMIN4 and cancer progression, including bladder cancer, renal cancer, lung cancer, and prostate cancer that yield a preliminary insight that the GEMINS protein family was related to the development of malignant tumors." (PMID 36284636, 2022). "It is remarkable that our results revealed that the SNPs and haplotypes were more correlated with the lung adenocarcinoma risk than other types of lung cancer, suggesting that the function of SNPs of the GEMIN4 gene may have cell specificity." (PMID 27669275, 2016). "Similar contradictory effects were found in GEMIN4*rs781 [gastric (OR = 1.46) versus bladder (OR = 0.76) and lung cancer (OR = 0.79)] and RAN*rs14035 results [HCC (OR = 3.11) versus CRC (OR = 0.75)]." (PMID 36672288, 2023). "Several studies documented that GEMIN4 facilitated cancer cell proliferation in renal cell carcinoma and lung cancer." (PMID 36284636, 2022). "Here, we selected five single nucleotide polymorphisms (SNPs) (rs7813, rs2740349, rs2291778, rs910924, rs595961) in two key microRNA biosynthesis genes (GEMIN4 and AGO1) and systematically evaluated the association between these SNPs, the gene-environment interaction and lung cancer risk." (PMID 27669275, 2016). "We determined its interaction with HindIII-digested chromatin fragments in a 45-kb region covering VPS53, FAM57A and GEMIN4 promoter regions in VCaP cells with ETH or DHT treatment and the lung cancer cell line A549." (PMID 36443337, 2022).
prostate carcinoma (4 papers, 2019 to 2021). A carcinoma that arises from epithelial cells of the prostate gland. "While we were undertaking this work, a paper reported the presence of a prostate cancer risk single-nucleotide polymorphism, rs684232, that suppresses AR-dependent expression of GEMIN4." (PMID 34725334, 2021). "Reduced GEMIN4 expression is associated with shorter clinical survival in prostate cancer patients, and knockdown of GEMIN4 is associated with reduced cell proliferation and colony formation." (PMID 34725334, 2021). "In brief, the results indicate that the rs684232 site and the target genes VPS53, FAM57A, and GEMIN4 are positively associated with prostate cancer cell malignancy, and the high expression for the three genes are associated with poor prognosis for cancer patients." (PMID 34445492, 2021). "Furthermore, Gemin4 is known to be regulated by the AR and associates with prostate cancer progression, which is highly relevant in the context of prostate cancer and CaMKK2 biology as the AR is also a major driver of CaMKK2 expression, disease progression and biology." (PMID 34725334, 2021). "Because our cell lines are prostate cancer derived, we chose to explore the interaction between Gemin4 and CaMKK2 further." (PMID 34725334, 2021). "We found that patients with higher expression levels of VPS53 (Log-rank p = 0.03), FAM57A (Log-rank p = 0.018), and GEMIN4 (Log-rank p = 0.016) had worse prostate cancer-specific survival probability." (PMID 34445492, 2021). "Patients with higher expression of VPS53, FAM57A, and GEMIN4 exhibited worse disease-specific survival probability, as demonstrated in the Kaplan–Meier survival analysis on the TCGA prostate cancer cohort." (PMID 34445492, 2021). "The results indicate that all three rs684232 target genes, VPS53, FAM57A, and GEMIN4, play essential roles during cell proliferation and colony formation of prostate cancer cells." (PMID 34445492, 2021). "The results indicate that the three target genes VPS53, FAM57A, and GEMIN4 may have a very important regulatory role in prostate cancer disease, and there may also be a synergistic promoting effect between them." (PMID 34445492, 2021). "For one of the regulatory SNPs, rs684232, we found that the variation altered chromatin binding of transcription factor FOXA1 on the DNA region and led to aberrant gene expression of VPS53, FAM57A, and GEMIN4, which play vital roles in prostate cancer malignancy." (PMID 34445492, 2021). "The risk allele diminishes androgen receptor (AR) occupancy, is associated with decreased H3K27ac levels, and downregulates the expression of VPS53, FAM57A, and GEMIN4, and the knockdown of VPS53, FAM57A, and GEMIN4 in prostate cancer cells results in an increase in cell viability." (PMID 33919522, 2021). "Interestingly, we also found that downregulation of VPS53, GEMIN4, and FAM57A genes led to shorter disease-free intervals for prostate cancer patients to the contrary." (PMID 34445492, 2021).
microcephaly (3 papers, 2020 to 2024). A congenital or acquired developmental disorder in which the circumference of the head is smaller than normal for the person's age and sex. "Recent studies have reported the association of germinal pathogenic variants in GEMIN4 with an inherited neurodevelopmental disorder characterized by microcephaly, cataracts, and renal abnormalities." (PMID 39202414, 2024). "Recently, pathogenic variants in GEMIN4 have been associated with neurodevelopmental features, microcephaly, cataract, and renal abnormalities (named NEDMCR, OMIM Phenotype MIM Number: 617913)." (PMID 35052432, 2021). "Pathogenic variants in GEMIN4 contribute to a hereditary disorder characterized by neurodevelopmental features, microcephaly, cataracts, and renal abnormalities (known as NEDMCR)." (PMID 35052432, 2021). "Gem nuclear organelle associated protein 4 (GEMIN4) is a protein-coding gene, and diseases related to GEMIN4 include cataract, kidney deformities, and neurodevelopmental disorders of microcephaly." (PMID 33250683, 2020).
breast carcinoma (2 papers, 2015 to 2023). "In general, knockdown of GEMIN4 may disturb cell proliferation ability in breast cancer cells." (PMID 37507701, 2023).
cataract (2 papers, 2021 to 2024). Partial or complete opacity of the crystalline lens of one or both eyes that decreases visual acuity and eventually results in blindness. "The same study linked several genes, including GEMIN4, to cataracts using developmental lens expression and gene-network analysis." (PMID 35052432, 2021).
gastric cancer (2 papers, 2017 to 2020). A primary or metastatic malignant neoplasm involving the stomach. "The present study investigates the influence of genetic variants in miRNA machinery genes (DROSHA, DICER, AGO1, and GEMIN4) on gastric cancer in Chinese Han population, further revealing the genetic mechanisms of gastric cancer occurrence and development." (PMID 29156806, 2017). "In gastric cancer, SNPs in miRNA machinery genes was strictly associated with cancer susceptibility and malignant behavior (Dicer and GEMIN4), or lymphatic metastasis (GEMIN4 and Ago1)." (PMID 33330058, 2020).
ovarian carcinoma (2 papers, 2016 to 2023). A malignant neoplasm originating from the surface ovarian epithelium. "Moreover, it has been reported that polymorphisms in GEMIN4 gene were related to the etiology as well as clinical outcome of multiple cancers like renal carcinoma, bladder cancer and ovarian cancer." (PMID 37507701, 2023). "GEMIN4 contributes to carcinogenesis in many cancers, such as kidney and ovarian cancer." (PMID 26991123, 2016).
renal carcinoma (2 papers, 2011 to 2023). A carcinoma arising from the epithelium of the renal parenchyma or the renal pelvis. "Previously, rs7813, also located in the GEMIN4 gene, which we observed to be the associated with higher sVCAM-1 levels in unadjusted models, was also associated with renal cancer in a case-control study." (PMID 21600003, 2011).
depression (1 paper, 2022). "In our own research, we looked for a relationship between GEMIN3 and GEMIN4 polymorphisms and the risk of depression." (PMID 36405016, 2022). "Does the GEMIN4 polymorphism increase the risk of depression by weaker suppression of steroidogenic factor 1 and therefore increase the activity of the HPA axis in carriers of the AA genotype?" (PMID 36405016, 2022). "The expression of the GEMIN4 protein is tightly associated with the biogenesis of related miRNAs, which may alter the risk of depression." (PMID 36405016, 2022). "Therefore, we decided to check whether the polymorphism of the GEMIN3 and GEMIN4 genes is associated with the risk of depression in the Polish population." (PMID 36405016, 2022). "The relationship between an occurrence of depression and the polymorphisms in GEMIN3 and GEMIN4 that we analyzed can also be explained by the mechanisms of involvement of these genes in the development of neoplasms." (PMID 36405016, 2022). "The dual role of rs7813/GEMIN4 is notable, where the G/A genotype in the codominant and over-dominant model protects against depression." (PMID 36405016, 2022). "The dual role of rs7813/GEMIN4 is noteworthy, where the G/A genotype in the codominant and over dominant model protects against depression." (PMID 36405016, 2022). "We have shown that in our population of patients, the risk of depression is almost doubled by polymorphic variants of the following genes: rs197388/GEMIN3 genotype A/A in the recessive model and rs3744741/GEMIN4 genotype T/T in the codominant and recessive model." (PMID 36405016, 2022). "They discovered that AGO1 rs636832 was significantly associated with depression and that GEMIN4 rs7813 did not affect susceptibility to depression." (PMID 36405016, 2022).
dysplastic nevi (1 paper, 2011). "Surprisingly, Dicer, Drosha and Gemin4 are down-regulated in melanoma in situ compared to invasive melanoma; in addition, Dicer is down-regulated in dysplastic nevi compared to common nevi, suggesting a global repression of miRNA biogenesis in these steps." (PMID 21698147, 2011).
esophageal squamous cell carcinoma (1 paper, 2017). Esophageal squamous cell carcinoma (ESCC) is a type of esophageal carcinoma (EC) that can affect any part of the esophagus, but is usually located in the upper or middle third. "Yang PW showed a borderline significant association between rs7813 in GEMIN4 and the prognosis of esophageal squamous cell carcinoma (ESCC)." (PMID 29156806, 2017).
esophagitis (1 paper, 2016). An acute or chronic inflammatory disease affecting the esophageal wall. "GEMIN4 was the only gene that reached borderline significance for esophagitis (P = 0.065)." (PMID 26991123, 2016).
hepatocellular carcinoma (1 paper, 2010). A malignant tumor that arises from hepatocytes. "A study found that the GEMIN4 rs7813 variant was associated with in vitro hepatocellular carcinoma cell line growth inhibition compared with the wild-type allele, suggesting that the amino acid change caused by this SNP might have physiologic significance." (PMID 20211803, 2010).
pneumonitis (1 paper, 2016). An inflammatory process affecting the lung parenchyma. "We observed that DGCR8 (p value: 0.010) and GEMIN4 (p value: 0.039) were significantly associated with pneumonitis, while XPO5 reached borderline significance (P = 0.087)." (PMID 26991123, 2016). "Gene based analysis supported a significant role of DGCR8 and GEMIN4 in the risk of pneumonitis." (PMID 26991123, 2016).
cancer (13 papers, 2011 to 2023). A tumor composed of atypical neoplastic, often pleomorphic cells that invade other tissues. "Functional studies revealed that miR-342 regulates genes involved with tumor cell death cancer pathways such as GEMIN4 (Gem nuclear organelle associated protein 4) and BMP7 (Bone morphogenetic protein 7)." (PMID 28574440, 2017). "Our results suggest that the Gemin4 rs7813 T > C and rs2740348 G > C polymorphisms are associated with cancer susceptibility." (PMID 27019773, 2016). "In the present analysis, the results of the meta-analysis of the Gemin4 rs7813 SNP revealed increased cancer risk for TT relative to TC + CC (OR = 1.18, 95% CI [1.05–1.32], Z-score = 2.75, P-value = 0.006)." (PMID 27019773, 2016). "The results of the meta-analysis of the Gemin4 rs2740348 SNP revealed increased cancer risk for GG relative to GC + CC (OR = 1.20, 95% CI [1.00–1.43], Z-score = 2.01, P-value = 0.044)." (PMID 27019773, 2016). "To date, no meta analysis has evaluated the relationship between polymorphisms in Gemin3 or Gemin4 and cancer risk." (PMID 27019773, 2016). "In our meta-analyses, we found that the Gemin4 rs7813 and rs2740348 SNPs were significantly associated with the risk of cancer." (PMID 27019773, 2016). "Several studies concerning the association between the Gemin3 rs197412, Gemin4 rs7813 and Gemin4 rs2740348 polymorphisms with cancer susceptibility have been published." (PMID 27019773, 2016). "Although several studies have investigated the association between the Gemin3 rs197412 T > C, Gemin4 rs7813 T > C and rs2740348 G > C polymorphisms with cancer susceptibility, the results were contradictory and uncertain." (PMID 27019773, 2016). "One SNP, rs2740349 (GEMIN4) was significantly associated with altered mRNA expression in carcinoma tissue, under the dominant model (FDR = 0.047)." (PMID 27107574, 2016). "The effects of the microRNA (miRNA) processing genes Gemin3 and Gemin4 on cellular signaling pathways could have a major impact on the risk of cancer." (PMID 27019773, 2016). "One of these three SNPs, rs2740349 (GEMIN4), was associated with altered mRNA expression in carcinoma tissue, and the two other SNPs, rs2059691 (PRKRA) and rs235768 (BMP2), were associated with altered levels of mRNA expression in normal colonic mucosa across genotypes." (PMID 27107574, 2016). "Hence, a metaanalysis based on the Preferred Reporting Items for Systematic reviews and Meta-Analyses (PRISMA) criteria was imperative to assess the associations between cancer susceptibility and the Gemin3 rs197412, Gemin4 rs7813 and Gemin4 rs2740348 polymorphisms." (PMID 27019773, 2016). "We then investigated the expression level of the three rs684232 target genes, VPS53, FAM57A, and GEMIN4, in cancer tissues and their effect on the clinical prognosis of cancer patients." (PMID 34445492, 2021). "In conclusion, our meta-analyses provided statistical evidence that the Gemin4 rs7813 and rs2740348 SNPs can predict cancer prognosis." (PMID 27019773, 2016). "Since the impairment of mature miRNAs is emerging as a feature of human cancers, given the critical function of Gemin3, Gemin4 and Ago1-4 in miRNA biosynthetic pathway." (PMID 27019773, 2016). "Three SNPs, rs2740349 (GEMIN4) in carcinoma tissue, and rs235768 (BMP2) and rs2059691 (PRKRA) in normal mucosa, were significantly associated with altered mRNA expression levels across genotypes after multiple comparison adjustment." (PMID 27107574, 2016). "In conclusion, the high expression of GEMIN4 were related to the poor prognosis of BLBC, and GEMIN4 might be as a carcinoma-promoting role in BLBC and could be an underlying molecular target for the treatment of BLBC." (PMID 37507701, 2023).
cancer (continued). "Further studies in larger series of patients are warranted to elucidate this question and determine the specific role of those cancer associated genes (INPP5A, CDX1, MB, CAMK2A, APOL6 vs. VPS53, FAM57A, GEMIN4, SFRS13, ELP2P, GLOD4, CSF2RA and IL3RA), differentially altered in both groups of tumors." (PMID 21811587, 2011). "Remarkably, the TCGA Pan-Cancer patients with a higher expression level of VPS53, FAM57A, and GEMIN4 also displayed decreased overall survival probability." (PMID 34445492, 2021). "In the TCGA prostate cohort, cancer tissues displayed significantly higher expression levels for the VPS53 (p = 0.014), FAM57A (p = 0.013), and GEMIN4 (p = 1.2 × 10−5) genes in comparison to adjacent normal tissues." (PMID 34445492, 2021). "There is therefore an interesting inverse relationship between the effect of GEMIN4 and CAMKK2 on cancer cell proliferation, as well as in the impact of androgen on their expression." (PMID 34725334, 2021). "When explored in the TCGA Pan-Cancer tissues, all the 33 cancer types displayed a positive pairwise correlation between VPS53, FAM57A, and GEMIN4." (PMID 34445492, 2021). "The SNP variations of GEMIN4 and AGO1 have been found to influence different types of cancer." (PMID 36551880, 2022). "Interestingly, for the 33 cancer types from the TCGA Pan-Cancer analysis project, up to 19, 16, and 16 cancer types displayed positive correlations for FOXA1 vs. VPS53, FOXA1 vs. FAM57A, and FOXA1 vs. GEMIN4, respectively." (PMID 34445492, 2021).
tumor (7 papers, 2017 to 2022). "miR-342 acts as a tumor suppressor and can sensitize ER-positive tumors to endocrine therapy by regulating genes involved in cell death pathways, such as gem nuclear organelle associated protein 4 (GEMIN4) and bone morphogenetic protein 7 (BMP7)." (PMID 32967267, 2020). "Consistent with our study, rs3742330 in DICER and rs7813 in GEMIN4 were found to participate in tumor progression." (PMID 29156806, 2017). "We observed significant over-expression of ADAR, ADARB1, DDX5/17/20, DGCR8, DICER1, DROSHA, EIF2C1-4 (AGO1-4), GEMIN4, POLR2A, TARBP2, TNRC6A and XPO5 in tumor tissue compared to adjacent mucosa." (PMID 31510013, 2019). "Previously, several researchers have reported the dysregulation and potential role of DICER, GEMIN4 and AGO1 in tumor progression, including GC." (PMID 29156806, 2017). "Finally, to test the biological relevance of the 17p13.3 locus genes, we pursued tumor cellular assays to demonstrate the effect of VPS53, FAM57A and GEMIN4 on PCa cellular phenotypes." (PMID 36443337, 2022). "In addition, the expression of DDX5/20, DGCR8, DICER1, DROSHA, EIF2C1-4, GEMIN4, TNRC6A and XPO5 was deregulated not only in tumor tissue, but also in corresponding liver metastases compared to adjacent tissue." (PMID 31510013, 2019). "The present data demonstrated that genetic variants in miRNA machinery genes had a significant association with GC susceptibility (DICER and GEMIN4) and malignant behavior such as tumor stage (DICER and GEMIN4) and lymphatic metastasis of GC (GEMIN4 and AGO1) in Chinese Han population." (PMID 29156806, 2017).
GEMIN4 also shares sentences with these, for which no sentence is quoted: neurodevelopmental disorder (2 papers); bladder cancer (1); chronic pancreatitis (1); cutaneous melanoma (1); epilepsy (1); lung adenocarcinoma (1); melanoma (1); pancreatitis (1); renal cell carcinoma (1); spinal muscular atrophy (1).